PDHX (pyruvate dehydrogenase complex component X)
Diseases named in the same sentence as PDHX in open-access papers:
PDHX is named in the same sentence as 49 diseases in open-access papers, as found by Europe PMC text mining. Sharing a sentence is not in itself a finding about the gene and the disease. The quoted sentences say what the papers report.
breast cancer (9 papers, 2018 to 2024). A primary or metastatic malignant neoplasm involving the breast. "Lastly, to obtain insight concerning how reduced PDHX expression impacts prognosis, we consulted the Sorlie Breast Cancer database to asses for any association of tumor PDHX expression with cancer recurrence and patient surficial status." (PMID 30012170, 2018). "Reduced PDHX expression is associated with poor survival in breast cancer." (PMID 38785550, 2024). "This low level of PDHX expression is associated with poor survival in breast cancer." (PMID 35053485, 2022). "In breast cancer, miR-27b affects mitochondrial oxidation by targeting PDHX, thereby promoting breast cancer progression." (PMID 35057851, 2022). "MicroRNA-27b targets PDHX, resulting in an altered metabolic configuration that is better suited to fuel biosynthetic processes and cell proliferation, thereby promoting breast cancer progression." (PMID 30012170, 2018). "To advance this objective, we reveal PDHX to be a target of miR-27b in breast cancer, and characterize the specific metabolic consequences of this dysregulated interaction." (PMID 30012170, 2018). "In support of this interpretation, evidence from the TCGA database shows PDHX expression is reduced in several breast cancer subtypes, including ductal and luminal subtypes when compared to normal tissue." (PMID 30012170, 2018). "To evaluate the role of PDHX in patient outcomes, we performed a Cox regression to evaluate survival in breast cancer patients using TCGA data." (PMID 30012170, 2018). "Plots were constructed for PDHX in breast cancer showing Distant-metastasis-free survival and reoccurrence-free survival." (PMID 30012170, 2018). "For example, miRNA‐27b promotes breast cancer via PDHX suppression." (PMID 39632246, 2024). "In the case of breast cancer, this may be explained by low levels of expression of the pyruvate dehydrogenase protein X (PDHX), a structural component of the PDH complex, an enzyme that controls the flow of metabolites from glycolysis to TCA." (PMID 38785550, 2024). "In breast cancer, it could be explained by a low level of expression of the PDHX component of the pyruvate dehydrogenase (PDH), which is an enzyme that controls the flow of metabolites from glycolysis to TCA." (PMID 35053485, 2022). "Interestingly, of the 11 different types of cancer available for comparison, breast cancer cells had among the lowest expression of PDHX, second only to myeloma." (PMID 30012170, 2018). "Below, we describe a series of experiments leading us to conclude that PDHX is a functional target of miR-27b and that this interaction has consequential effects on cell metabolism which facilitate cell growth and progression in breast cancer." (PMID 30012170, 2018). "To compare the significance of PDHX suppression in breast cancer specifically when compared with other cancer types, we utilized the Staunton Cell Line Statistics database (accessed through the Oncomine data portal) to compare PDHX expression across a panel of different types of cancer cell lines." (PMID 30012170, 2018). "In breast cancer, miR-27b has been reported to target the 3′ untranslated region (3′UTR) region of pyruvate dehydrogenase complex component X (PDHX), limiting the conversion of pyruvate in the tricarboxylic acid cycle (TCA)." (PMID 33430468, 2021). "miR-27a could upregulate PDHX and limit the convention of pyruvate to the tricarboxylic acid cycle (TCA); this leads to the accumulation of pyruvate and encourages the synthesizing of lactic acid which facilitates cell growth and the progression of breast cancer." (PMID 36230935, 2022).
pyruvate dehydrogenase deficiency (5 papers, 2016 to 2023). A rare neurometabolic disorder characterized by a wide range of clinical signs with metabolic and neurological components of varying severity. "In fact, defects on PDHX caused pyruvate dehydrogenase deficiency, resulting in lactic acidosis and neurological dysfunction in infancy and early childhood." (PMID 34440082, 2021). "In fact, mutation of the PDHX gene was shown to result in pyruvate dehydrogenase deficiency in Moroccan patients, supporting our hypothesis." (PMID 30509175, 2018). "Pyruvate dehydrogenase deficiency caused by a new mutation of PDHX gene in two Moroccan patients." (PMID 27896281, 2016).
colorectal cancer (4 papers, 2014 to 2022). A primary or metastatic malignant neoplasm that affects the colon or rectum. "MiR-26a regulates glucose metabolism of colorectal cancer cells by direct targeting the PDHX, which inhibits the conversion of pyruvate to acetyl coenzyme A in the citric acid cycle." (PMID 24935220, 2014). "We have identified the pyruvate dehydrogenase protein X component (PDHX) as a direct target of miR-26a that is involved in the biological processes of glucose metabolism in colorectal cancer (CRC) cells." (PMID 24935220, 2014). "It was showed that in colorectal cancer cells the glucose metabolism was regulated by miR-26a direct targeting the PDHX, which inhibits the conversion of pyruvate to acetyl coenzyme A in the citric acid cycle to require the glucose uptake to the energy needs of cancer cells." (PMID 29113313, 2017).
breast tumor (3 papers, 2018 to 2022). "PDHX, which takes part in encoding the pyruvate dehydrogenase (PDH) complex, was deficient in human breast tumor samples, and low levels of PDHX were also associated with decreased patient survival." (PMID 35995782, 2022). "In human breast tumor samples, PDHX expression was deficient, and low levels of PDHX were associated with reduced patient survival." (PMID 30012170, 2018). "To confirm that PDHX protein is also reduced in breast tumors, we used pairwise cancer and normal tissue samples in our collection and probed PDHX protein expression by western blot." (PMID 30012170, 2018). "As seen in our analysis of breast tumors, the expression of PDHX and miR-27b displayed a negative correlation." (PMID 30012170, 2018).
esophageal squamous cell carcinoma (2 papers, 2022 to 2023). Esophageal squamous cell carcinoma (ESCC) is a type of esophageal carcinoma (EC) that can affect any part of the esophagus, but is usually located in the upper or middle third. "It has been demonstrated that PDH component X (PDHX) is an essential gene for the cell growth of esophageal squamous cell carcinoma (ESCC) through metabolic regulations." (PMID 35216362, 2022).
Alzheimer disease (1 paper, 2022). A progressive, neurodegenerative disease characterized by loss of function and death of nerve cells in several areas of the brain leading to loss of cognitive function such as memory and language. "According to the interaction network of PDK4 from the String database, DLD is involved in caloric restriction (CR)-preventable mitochondrial ROS in yeast aging process, and PDHX reduction is related to aging diseases, such as Alzheimer’s disease, glucose intolerance, and cancer." (PMID 35372351, 2022).
colon cancer (1 paper, 2014). "The expression of miR-26a is inversely associated with the level of its targeting protein PDHX in several colon cancer cell lines with different malignancy potentials." (PMID 24935220, 2014). "The PDHX expression at the mRNA and protein level in several colon cancer cell lines was quantified with real-time PCR and Western blot analysis respectively." (PMID 24935220, 2014).
esophageal carcinoma (1 paper, 2023). A primary or metastatic malignant neoplasm involving the esophagus. "Moreover, some CRGs, including PIH1D2, SLC23A2, SLC25A5, ATP7A, PDHX and COX7B, were reported to be tightly linked with the grading and immune infiltration of esophageal carcinoma." (PMID 37380924, 2023).
glaucoma (1 paper, 2021). Increased pressure in the eyeball due to obstruction of the outflow of aqueous humor. "Other variants in genes for IFT172, DFNB31, PDHX, SALL2, BMP4 and GPR179 by WES were excluded as deleterious and pathogenic mutations, and none of them was reported as a stronger/convincing glaucoma causing variant in the literature." (PMID 34399712, 2021).
glioblastoma (1 paper, 2017). The most malignant astrocytic tumor (WHO grade IV). "On the other hand, IDH1MUT glioma showed higher expression levels of PDHA (in glioblastoma), PDHB (in LGG) and PDHX as compared to IDH1WTglioma." (PMID 28467784, 2017).
hepatocellular carcinoma (1 paper, 2025). A malignant tumor that arises from hepatocytes. "Here, we demonstrate that the acetylation of Lys 488 of pyruvate dehydrogenase complex component X (PDHX) commonly occurs in hepatocellular carcinoma, disrupting PDC assembly and contributing to lactate-driven epigenetic control of gene expression." (PMID 39311688, 2025).
liver cancer (1 paper, 2025). An epithelial or non-epithelial malignant neoplasm that arises from the liver. "Collectively, our cellular and clinical data revealed that PDHX Lys 488 acetylation is upregulated in HCC, and is highly associated with liver cancer progression." (PMID 39311688, 2025). "Taken together, these data demonstrated that PDHX Lys 488 acetylation is an important determinant of liver cancer proliferation, and that DCA treatment specifically target the growth of glycolysis-dependent tumors through enhancing PDC activity." (PMID 39311688, 2025). "PDC activity levels were also shown to be significantly lower in patients with clinical liver cancer compared to healthy subjects, an observation that could be attributed to high levels of PDHX Lys 488 acetylation in patients." (PMID 39311688, 2025).
lung carcinoma (1 paper, 2014). "Our results provided experimental evidences to verify the bioinformatics speculation that miR-26a has a high possibility to regulate PDHX in lung cancer." (PMID 24935220, 2014).
lung disease (1 paper, 2020). "Although EHF and APIP are the nearest genes to the intergenic chr11 GWAS locus with significant lung disease association p-values, PDHX is best predicted to be regulated by SNPs in the region based on current gene expression data." (PMID 33253230, 2020).
paroxysmal dystonia (1 paper, 2020). "Three patients with PDHA1 mutations (3/7: 43%) and three with PDHX mutations (3/5: 60%) are under ketogenic diet with clearly beneficial effects on childhood-onset epilepsy or paroxysmal dystonia." (PMID 33092611, 2020).
protein deficiency (1 paper, 2016). "We diagnosed pyruvate dehydrogenase E3-binding protein deficiency (OMIM 245349) by detecting a homozygous stop mutation in the PDHX gene (c.1336C>T in exon 11 causing p.R446* according to NM_003477.2)." (PMID 27317552, 2016).
cancer (13 papers, 2017 to 2025). A tumor composed of atypical neoplastic, often pleomorphic cells that invade other tissues. "Since PDHA1 acetylation was previously reported, we focused on exploring the role of PDHX acetylation in cancer cells." (PMID 39311688, 2025). "In contrast, the proliferation of cells expressing PDHX K488R was hardly affected by DCA, indicating that cancer cells with high level of PDHX Lys 488 acetylation are the target of DCA drugs." (PMID 39311688, 2025). "Taken together, these results show that PDHX Lys 488 acetylation results in diminished PDC assembly in cancer cells." (PMID 39311688, 2025). "A strategy cancer cells apply to elevate the glycolysis rate is to control the active enzymes in the pyruvate cycle, pyruvate dehydrogenase complex component X (PDHX) and pyruvate dehydrogenase complex (PDK)." (PMID 37161350, 2023). "Through first overexpressing miR-27b, cancer cells are able to inhibit PDHX expression and subsequently function of the PDH complex itself." (PMID 30012170, 2018). "In the context of cancer, acetylation of pyruvate dehydrogenase complex component X (PDHX) has been demonstrated to disrupt the assembly of PDC, resulting in elevated lactate production and subsequent lactylation-mediated gene expression, thereby facilitating tumor progression." (PMID 40867622, 2025). "K488Q expressing cells proliferated at similar rates with cells expressing PDHX WT which might be explained by our observation that WT PDHX is highly acetylated in cancer cells." (PMID 39311688, 2025). "Importantly, analysis of clinical HCC samples demonstrated that PDHX Lys 488 acetylation levels greatly increased in cancer tissues compared with the surrounding healthy tissue." (PMID 39311688, 2025). "Since PDHX Lys 488 acetylation rewired glucose metabolism to glycolysis in cancer cells, we examined whether PDHX Lys 488 acetylation affects the therapeutic effect of DCA." (PMID 39311688, 2025). "Notably, among the histones lactylation modifications that we tested, H3K56la was dramatically increased after suppression of PDHX in cancer cells." (PMID 39311688, 2025). "Although previously it has been shown that miR-26a could affect glucose metabolism in cancer cells by targeted-regulation of expression of PDHX mRNA and protein." (PMID 31936222, 2020). "Thus, we selected PDHX as the primary target to investigate further because of its significance in cell energy metabolism, an area of growing interest in cancer biology." (PMID 30012170, 2018). "Therefore, we tested whether the accumulation of lactate induced by PDHX-depletion promotes protein lactylation in cancer cells." (PMID 39311688, 2025). "Collectively, these data suggested that PDHX Lys 488 acetylation inhibits PDC activity and contributes to metabolic reprogramming of cancer cells." (PMID 39311688, 2025).
tumor (10 papers, 2018 to 2025). "We found that H3K56la was present within the promoters of oncogenes that are stimulated by the acetylation of PDHX, thereby providing new insights into understanding the contributions of glycolysis to tumor progression." (PMID 39311688, 2025). "RNA was collected from these samples and analyzed by qRT-PCR., which showed a significant decrease in PDHX expression in the tumor tissues compared to the control tissue group." (PMID 30012170, 2018). "The enzymatic activity of p300 and the levels of acetyl-CoA within cells are both regulated by signaling pathways in tumor cells, suggesting that upstream signaling pathway(s) within tumor cells may play a pivotal role in p300-mediated acetylation of PDHX." (PMID 39311688, 2025). "In addition, through in vitro and in vivo experiments, we found that DCA can specifically inhibit glycolysis-dependent tumor growth, and tumors with high levels of PDHX Lys 488 acetylation are the suitable target of DCA drugs." (PMID 39311688, 2025). "However, in tumor cells, the rate of pyruvate production often exceeds the rate of PDHx-mediated pyruvate catabolism, and in some tumors, the activity of PDHx is inhibited by pyruvate dehydrogenase kinase (PDK)." (PMID 38933335, 2024). "In one study using TgMMTV-neu mouse, three early-stage tumor antigens (PDHX, STK39, and OTUD6B) were identified by serological analysis of cDNA expression libraries (SEREX) screen that could serve as superior antigen targets for the inhibition of tumor growth." (PMID 37513965, 2023). "Moreover, the level of PDHX was slightly upregulated in GBC tumor tissues, compared with normal tissues." (PMID 34485121, 2021). "Thus, in the future, we aimed to investigate whether miR-181b-5p could promote tumor cell migration via targeting PDHX." (PMID 34485121, 2021). "These investigations determined that PDHX, a key protein that bridges the PDC complex, functions to regulate PDC assembly, thereby strongly effecting PDC activity to impact tumor progression." (PMID 39311688, 2025). "The high basal levels of PDHX acetylation led to the observation that PDHX-WT and PDHX-K488Q exhibit similar effects on the interaction between PDHX and DLAT, as well as on tumor proliferation." (PMID 39311688, 2025). "Thus, it is of interest to investigate the effect of PDHX Lys 488 acetylation, which also results in PDC deactivation, on tumor-cell proliferation." (PMID 39311688, 2025). "Disruption of interactions between DLAT and the pyruvate dehydrogenase complex component X (PDHX) hinders the assembly of PDC, which can be inactivated, thus promoting a shift from the TCA cycle to aerobic glycolysis and an increase in lactate production, and ultimately promoting tumor progression." (PMID 39979835, 2025).
infection (2 papers, 2021 to 2022). The state of being infected such as from the introduction of a foreign agent such as serum, vaccine, antigenic substance or organism. "The results showed that knock down of HK2, PDHX, and GLUT1 significantly inhibited SGIV infection, demonstrated by the marked reduction in both transcription and protein expression of SGIV MCP." (PMID 35432224, 2022). "Of note, PDHX activity and protein expression was promoted at 12 h p.i., suggested that SGIV infection induced PDHX activation and promoted pyruvate into TCA cycle at the early stage of infection." (PMID 35432224, 2022).
metabolic disorders (2 papers, 2015 to 2023). "In our study, ovarian HK1, HK2, PDHX and ACSS2 were repressed but FBP2 and ALDH1B1 were activated in DHT-treated rats, further complicating the metabolic disorders in those groups." (PMID 25887459, 2015).
PDHX also shares sentences with these, for which no sentence is quoted: cholestasis (2 papers); acute lymphoblastic leukemia (1); acute myeloid leukemia (1); Alexander disease (1); Allergy (1); atopic asthma (1); B-cell acute lymphoblastic leukemia (1); biotinidase deficiency (1); Cerebellar atrophy (1); Cerebral atrophy (1); ciliopathies (1); epilepsy syndrome (1); gallbladder cancer (1); glioma (1); Glucose intolerance (1); glycogen storage diseases (1); Hartnup disease (1); heart failure (1); Hypercholesterolemia (1); lactic acidosis (1); leukemia (1); liver failure (1); maple syrup urine disease (1); mitochondrial disease (1); myeloma (1); neuroblastoma (1); non-small cell lung carcinoma (1); rheumatic diseases (1); type I citrullinemia (1).